RIIAD1 (regulatory subunit of type II PKA R-subunit domain containing 1)
Synonyms: C1orf230; FLJ36032; NCRNA00166
Tractability: No criterion of Open Targets' tractability assessment is met for any kind of drug.
Gene: Protein-coding gene on chromosome 1 (151,710,433 to 151,729,805, forward strand). Ensembl gene ENSG00000178796.
Subcellular location (Human Protein Atlas): Cytosol; Nucleoplasm
Genetic constraint (gnomAD): Loss-of-function variants: 3 observed, 0.95 expected, observed/expected ratio (o/e) 3.15. That is too few expected variants to judge how well the gene tolerates losing a copy. Missense variants: 41 observed, 17.78 expected, observed/expected ratio (o/e) 2.31. Synonymous variants: 23 observed, 10.13 expected, observed/expected ratio (o/e) 2.27.
Homologues: Orthologues: macaque RIIAD1 (92% identical), dog RIIAD1 (86% identical), rabbit RIIAD1 (80% identical), rat Riiad1 (79% identical), pig RIIAD1 (78% identical), mouse Riiad1 (77% identical), chimpanzee RIIAD1 (76% identical), zebrafish si:dkey-71b5.6 (55% identical), tropical clawed frog riiad1 (40% identical). Paralogues in human: SPA17 (23% identical), GAP43 (10% identical).
Diseases named in the same sentence as RIIAD1 in open-access papers:
RIIAD1 is named in the same sentence as 3 diseases in open-access papers, as found by Europe PMC text mining. Sharing a sentence is not in itself a finding about the gene and the disease. The quoted sentences say what the papers report.
Infertility (1 paper, 2022). "In fact, a recent paper mentioned RIIAD1 as co-expressed with the a-kinase anchor protein 3AKAP3, a gene whose knockdown was shown to induce infertility in male mice." (PMID 36064320, 2022).
tumor (2 papers, 2020 to 2023). "CpG islands located at RIIAD1, ENPP2, ESPN, and ETS1, were hyper-methylated in BC tumor." (PMID 38082340, 2023). "Besides, expressions of ENPP2 and ETS1 were significantly decreased in BRCA tumor samples, and ESPN and RIIAD1 were significantly elevated in BRCA tumor samples compared with adjacent normal samples." (PMID 32412047, 2020).
RIIAD1 also shares sentences with these, for which no sentence is quoted: cancer (1 paper).